FASN (fatty acid synthase)
Diseases named in the same sentence as FASN in open-access papers (continued):
Sharing a sentence is not in itself a finding about the gene and the disease.
tumor (continued). "FASN inhibition also suppressed genes involved in production of intracellular second messenger arachidonic acid and androgen hormones, both of which promote tumor progression." (PMID 23741342, 2013). "It has been so far reported that FASN produces fatty acids as essential constituents of membrane phospholipids and important substrates for energy metabolism and that FASN inhibition can induce decrease of the lipid production in tumor cells." (PMID 23741342, 2013). "The level of fatty acid synthase (FASN) expression in tumor cells was only moderately increased in the majority of tumor cells, which suggests that PET/CT imaging with radiolabeled acetate or choline may not be effective, but should also be explored." (PMID 22875335, 2013). "We also analysed FASN protein expression levels of each individual animal tumour." (PMID 22177475, 2011). "Concerning bioavailability, G28UCM reached the target tissue in the responding xenografts, since the in vivo FASN inhibition was of 30% (see SD), which is similar to the reported intra-tumour 40% inhibition of FASN activity 12 hours after intraperitoneal injection of other FASN inhibitors." (PMID 22177475, 2011). "We discovered that the co-localisation of Mb with FASN might give a hint towards the FA-binding function of tumour Mb." (PMID 20531416, 2010). "Moreover, several reports have shown that FASN and related lipogenic enzymes play important roles in tumour cell survival at multiple levels." (PMID 19352381, 2009). "It has been reported that fatty acids (FAs) synthesis is increased in many human tumors while inhibition of fatty acid synthase (FASN) could suppress tumor growth." (PMID 18523653, 2008). "Accordingly, we found FASN expression to be much stronger in tumours than in BPH." (PMID 17146477, 2007). "Through FASN-driven de novo lipogenesis, meCAFs supply pancreatic cancer cells with fatty acids that support membrane synthesis, energy production, and redox balance, thereby promoting tumor proliferation, survival, and resistance to therapy such as gemcitabine." (PMID 40940809, 2025). "Consequently, the combination of FASN inhibitors and T cell activators may enhance the response of tumor cells to FASN inhibitors." (PMID 39757995, 2025). "Additionally, FASN enhances the immune evasion capability of tumor cells." (PMID 40936898, 2025). "Although our hypothesis certainly needs further experimental validation, supporting reports suggest that FASN-mediated changes in specific fatty acids can promote tumor cell migration, and CD9 overexpression is associated with cells transitioning to a metastatic state." (PMID 40163697, 2025). "Similarly, coupling CD36 inhibition with FASN blockade may restrict both exogenous and endogenous lipid supply, collectively reprogramming the tumor microenvironment toward an immune-responsive state." (PMID 41312365, 2025). "Furthermore, effectively inhibiting FASN expression can significantly block tumor cell growth." (PMID 40936898, 2025). "Given that FASN and RUNX2 are also associated with immune-related pathways, including cytokine signaling and immune cell infiltration, their lactate-regulatory roles may exert multifaceted effects that go beyond intrinsic tumor growth." (PMID 40703521, 2025). "Moreover, FASN appears to augment the traits of CSCs and facilitate the formation of tumor spheres." (PMID 40901481, 2025). "Given the essential role of sterol regulatory element-binding protein 1 (SREBP-1) and fatty acid synthase (FASN) in tumor lipogenesis, it is plausible that OC may interfere with lipid biosynthetic pathways, thereby depriving tumor cells of essential precursors for proliferation and survival." (PMID 40564985, 2025). "Moreover, FASN silencing reduced tumor growth and lung metastasis in vivo." (PMID 40148316, 2025).
tumor (continued). "This metabolic reprogramming not only supports the energy requirements of tumor cells but also enhances their survival and invasive capabilities by regulating the activities of enzymes involved in lipid droplet formation, fatty acid oxidation, and synthesis (e.g., FASN, CPT1A)." (PMID 40717587, 2025). "For example, studies could consider a triple therapy design, simultaneously targeting glucose metabolism (LDHA inhibitor), lipid metabolism (FASN inhibitor), and immune checkpoints (anti-PD-1), and remodeling the “hot tumor” microenvironment through metabolic reprogramming." (PMID 40426972, 2025). "However, this tumor-suppressive effect was weakened after compensatory overexpression of FASN." (PMID 38291470, 2024). "Furthermore, there have been multiple inhibitors developed against FASN, for example, cerulenin, which increases survival rates and improves anti-tumour immune response in xenograft ovarian models, and orlistat—a drug which demonstrates synergy with cisplatin in vivo." (PMID 39181893, 2024). "However, in tumor cells, lipids de novo synthesized by FASN are preferentially chosen as phospholipids that may be involved in cell signaling." (PMID 38819674, 2024). "Therefore, targeting FASN may enhance antitumor immunity and represents a promising approach for tumor immunotherapy." (PMID 39624081, 2024). "However, overexpression of FASN, either alone or in association with other oncogenes such as c-Met and mutant NRas, did not drive liver carcinogenesis in the mouse, assigning a tumor-supporter role rather than a bona fide oncogenic function to FASN." (PMID 39064589, 2024). "Moreover, new research declared that high glucose can switch PTEN from a tumor suppressor to a tumor promoter by triggering its neddylation, and then this neddylated PTEN move to the nucleus and decrease the association of FASN with TRIM21 via dephosphorylating FASN in BC." (PMID 38167440, 2024). "In addition, LINC00504 accelerated tumor progression in CC cells via the c-Myc/FASN axis." (PMID 38184562, 2024). "However, whether FASN is an intrinsic mechanism of tumor cell defense against T cell immunity remains unexplored." (PMID 39349429, 2024). "In addition, FASN regulates the tumor vasculature by inducing secretion angiogenic factors." (PMID 38731601, 2024). "Moreover, DCs educated by FASN-elevated tumor cells also have defects in T cell priming." (PMID 38216787, 2024). "Furthermore, in rapidly proliferating tumor cells, the synthesis of fatty acids is accompanied by increased expression of major fatty acid synthesis enzymes including acetyl CoA carboxylase and FASN." (PMID 37078067, 2023). "Furthermore, genetic knockdown of FASN efficiently reduced SPDEF expression in tumor spheres." (PMID 36809297, 2023). "Finally, FASN is involved in immune escape by repressing the activation of pro-inflammatory cells and promoting the recruitment of M2 macrophages and T regulatory cells in the tumor microenvironment." (PMID 36934087, 2023). "This causes apoptosis in tumor cells to overexpress FASN without affecting non-malignant cells." (PMID 37920207, 2023). "Therefore, we hypothesized that TA on the ICG-Glow NPs efficiently binds to EGFR, CXCR4, FASN, and other oncoproteins, thus facilitating tumor specific binding/targeting which can further provide a novel option for tumor specific probe development." (PMID 37151801, 2023). "In addition, adenosine monophosphate-activated protein kinase (AMPK)/mammalian target of Rapamycin (mTOR) 48 and signal transducer and activator of transcription 3 (STAT3) 49 signaling pathways have also been reported to mediate the regulation of FASN in tumor proliferation and metastasis." (PMID 37497413, 2023). "Globally, all these cell programs regulated by altered FASN expression heavily contributed to the assumption that FASN might function as a metabolic intermediate of oncogenesis linking energy, anabolism, carcinogenesis, and tumor invasiveness." (PMID 36753044, 2023).
tumor (continued). "Additionally, FASN connects the metabolism of immune cell control and the tumor microenvironment." (PMID 36555243, 2022). "Overall, we speculated that up-regulation of FASN in tumors maybe promote tumor progression." (PMID 36555243, 2022). "Furthermore, FASN promoter DNA methylation can be used as a tumor prognosis marker." (PMID 36555243, 2022). "However, much additional work will be required to fully understand the regulatory actions that could emanate from FASN activity in normal and tumor cells." (PMID 35791446, 2022). "On the other hand, pharmaceutical and genetic suppression of fatty acid synthase (FASN) has been shown not only to protect T cells from apoptosis within the TME triggered by repeated T cell receptor (TCR) activation but also to boost T cell immunity along with its antitumor efficacy on tumor cells." (PMID 35743298, 2022). "Finally, we confirmed the tumor-suppressive effect of mir-195-5p through FASN." (PMID 36555243, 2022). "Finally, we proved that mir-195-5p may inhibit tumor activity via FASN inhibition, which has therapeutic drug development value." (PMID 36555243, 2022). "Multiple authors are currently investigating selective ways to inhibit this enzyme activity as it may cause tumor cell death while respecting non-tumor cells; this is because of the observed dependence of part of the tumor cells on fatty acid synthase for the maintenance of the cell membrane." (PMID 35456969, 2022). "Also, FASN is critical in sustaining the biological features of malignant tumor cells." (PMID 35350838, 2022). "In addition, the abnormal elevation of fatty acid synthase in CAFs may enhance the aggressiveness of tumor cells." (PMID 34977870, 2021). "FASN inhibition could thus provide a mechanism to restore anti-tumour immunity." (PMID 34944851, 2021). "Similarly, inhibition of fatty acid synthase (FASN) inhibited tumor growth." (PMID 33718207, 2021). "The effects of FASN-targeted therapy by orlistat combined either with enzalutamide or castration could down-regulate the activity of NF-κB, which was closely associated with phosphorylations of AKT and ERK, resulting in tumor growth inhibition in AIPC." (PMID 33974005, 2021). "Interestingly, FASN is abnormally expressed in tumor tissues and mediates tumor evolvement." (PMID 35070947, 2021). "Consequently, therapeutic inhibition of FASN activity might be either highly detrimental or ineffective for HCC treatment in molecularly different tumor subsets." (PMID 33187130, 2020). "Furthermore, a panel of five genes including FASN (ACOT8/ACSL5/FASN/HMGBCS2/SCD1) has been reported to display a improved prognostic performance than validated clinical risk scales, and it is applicable for early discovery of CRC and tumor recurrence." (PMID 33194695, 2020). "Therefore, tumours that have an aggressive phenotype will show increased FASN expression." (PMID 32698888, 2020). "Ample evidence has revealed that FASN may act as a biomarker in promoting tumor progression, including cell proliferation, cell adhesion, migration, and invasion, as well as pseudopodia formation, which plays a critical role in PCa proliferation and metastasis." (PMID 32655718, 2020). "The PyMT is an extraordinarily penetrant oncogene (hundreds of tumor foci are simultaneously developed in each mammary gland), and Cre recombinase activity was not sufficient to delete the FASN gene in 100% of the breast epithelial cells, thus allowing the development of FASN-positive tumor foci." (PMID 31676791, 2019). "Because pharmacological and genetic ablation of FASN overcomes tumor regrowth and metastasis after antiangiogenic therapy withdrawal, it might be worthwhile to evaluate whether the CCN1 Æ FASN angiogenesis/lipogenesis axis is responsible for the resistance to antiangiogenic therapies." (PMID 27713913, 2016). "Indeed, elevated FASN expression has been linked to negative prognosis and reduced disease-free survival in many other neoplasms." (PMID 25947066, 2015).
tumor (continued). "However, its reactivity to human tumor cell lines suggests the possibility of occurrence of autoantibodies with similar reactivity to K94 antibody in tumor patients’ sera, as in the case of anti-FASN autoantibody." (PMID 23128437, 2013). "Although orlistat is an inhibitor of FASN which is reported to be required by Mφ for phagocytic ability and other activation associated functions, orlistat-administration to tumor-bearing mice did not inhibit the expression of FASN in BMC or BMDM (data not shown)." (PMID 24349275, 2013). "In addition, PUFAs suppress fatty acid synthase enzyme and thus, induce apoptosis of tumor cells." (PMID 21917129, 2011). "Furthermore, tumor induction by certain oncogenes causes the activation and expression of enzymes for the de novo synthesis of fatty acids such as acetyl-CoA carboxylase (ACC) and fatty acid synthase (FASN)." (PMID 22203527, 2011). "Indeed, studies have suggested that FBI-1 could repress retinoblastoma gene, another well-known tumor suppressor gene and could activate fatty-acid synthase gene (FASN)." (PMID 21176152, 2010). "To assess the potential artificial synthetic lethality and overcome PARPi resistance by inhibiting FASN activity in-vivo, we tested the combination synergism between 5HLS and talazoparib on the BRCA1 wild-type TNBC xenograft tumor." (PMID 41158759, 2026). "Targeting the c-Myc/GRPEL1 axis to block FASN-regulated FA synthesis inhibited PDAC cell proliferation and tumor growth in both cell models and patient-derived organoids (PDOs), whereas FA supplementation partially reversed this inhibitory effect." (PMID 41644513, 2026). "Single-cell analysis revealed that FASN and ACACA were predominantly expressed in tumor cells, while SPP1 was enriched in macrophages/monocytes." (PMID 42198359, 2026). "In vivo, lipid nanoparticle-encapsulated echinomycin rapidly suppressed HRE, SRE, and ARE activity, reduced peri-hypoxic induction of FASN and GLUT3, inhibited tumor growth, and eliminated lung metastasis." (PMID 42237006, 2026). "These pathways enhance DNL by modulating the expression of related enzymes, such as FASN and ACC, promoting tumor growth." (PMID 40533802, 2025). "Subsequent ST analysis demonstrated that in Case 1, the FASN and ACC1 genes, which are involved in fatty acid synthesis, were significantly upregulated in the tumor tissues." (PMID 39425259, 2025). "Intraperitoneal injection of PC (18:0|18:1) reversed the effect of FASN knockdown on MC38 xenograft growth, as evidenced by the tumor image, tumor weight, and tumor volume." (PMID 40148316, 2025). "Another study showed that FASN inhibitors decreased aberrant lipid accumulation in the TIME, which promoted the activation and accumulation of DCs as well as anti-tumor T cells, and re-sensitized tumor cells to immunotherapy." (PMID 39757995, 2025). "Studies have found that a variety of key metabolic enzymes involved in fatty acid synthesis and oxidation are upregulated in breast cancer and play an important role in tumor growth, such as SREBP1, ACC1, FASN, SCD, and ELOVL1." (PMID 40002387, 2025). "Nonetheless, despite successfully inhibiting BRD1, we observed a concurrent downregulation of SREBF1, FASN and SCD1 within the HCC tumor tissue." (PMID 39962068, 2025). "It has also been shown that the combination of two distinct FASN inhibitors, orlistat and TVB-2640, with anti-PD-L1 antibodies significantly inhibits tumor growth in vivo." (PMID 40161377, 2025). "For instance, fatty acid synthase (FASN) inhibitors like TVB‐2640, currently in clinical trials, show promise in reducing tumor growth and enhancing chemotherapy efficacy." (PMID 40391753, 2025). "We evaluate the growth of tumor cell lines in four distinct experimental groups: the control group, the PUMA knockdown group, the control group treated with C75 (a FASN inhibitor, 35 μM), and the PUMA knockdown group treated with C75." (PMID 40533456, 2025).
tumor (continued). "Under hypoxia, tumor cells convert acetate to acetyl-CoA via ACSS2, activating lipogenic genes (e.g., FASN) to fuel de novo lipogenesis and support growth." (PMID 40718481, 2025). "Co-inhibition of FASN with two mechanistically distinct agents, orlistat and TVB-2640, combined with an anti-PD-L1 antibody robustly suppressed tumor growth in vivo, underscoring the rationale for integrating metabolic inhibition with checkpoint blockade." (PMID 41236698, 2025). "Experimental studies have shown that pharmacological inhibition or genetic silencing of FASN, SCD1, or CD36 can impair lipid metabolic flux, disrupt membrane architecture, and suppress tumor growth and chemoresistance." (PMID 41350297, 2025). "Further, IHC labeling of subcutaneous xenograft tumor tissue demonstrated that MARCH8 overexpression suppressed the expression of ACC1 and FASN." (PMID 40379644, 2025). "To date, clinical trials targeting lipid metabolism have focused on FASN inhibitors, particularly TVB-2640, one of the most advanced lipid metabolism-targeted drugs, which effectively suppresses tumor growth." (PMID 41476608, 2025). "Consistently, IHC assays confirmed decreased expression of FASN, ACLY, and SCD in tumor tissues derived from VPS72 knockdown cells." (PMID 40305746, 2025). "Lipid-targeting (e.g., FASN, ACC, SCD1 inhibitors) acts as a metabolic trap: impairing tumor lipid supply, altering membrane composition and increasing vulnerability to immune attack." (PMID 41394868, 2025). "The regulation of FASN by miR‐195 affects HCC progression by downregulating Wnt expression and inhibiting FASN activity, which impairs tumor cell growth and metastasis." (PMID 40391753, 2025). "In vitro and in vivo models show that NiNPs activate the CDK1/STAT3/FASN axis to disrupt FAM homeostasis, conferring metabolic advantages for tumor cell proliferation and migration." (PMID 41226659, 2025). "These tumors often exhibit elevated expression of lipid-related enzymes (e.g., FASN, ACC), transporters (CD36), and regulators (SREBP1), all of which support tumor growth, metastasis, and immune evasion." (PMID 40487761, 2025). "In preclinical HCC models, pharmacological inhibition of FASN restores T-cell effector function, increases MHC I expression, enhances tumor antigen presentation, and cooperates with PD-1/PD-L1 blockade." (PMID 41514551, 2025). "The FASN inhibitor orlistat, approved by the FDA, synergizes with gemcitabine in pancreatic cancer by inducing ER stress and reducing tumor stemness, thereby overcoming chemoresistance." (PMID 41350297, 2025). "This complex activates and regulates downstream lipogenic factors, such as fatty acid-binding protein 4 (FABP4), FASN, and ACC, enhancing the ability of tumor cells to synthesize fatty acids." (PMID 40830338, 2025). "In a recent preclinical study, a FASN inhibitor promoted T helper cell 1 (Th1) infiltration and activation, increased IFN-γ production, and induced apoptosis of tumor cells." (PMID 39757995, 2025). "Several circRNAs participate in the lipid metabolic reprogramming of tumor cells by activating and regulating the AMPK complex, driving de novo FA synthesis, and altering the cellular distribution of FASN mRNA." (PMID 39402211, 2025). "Western blot analysis further assessed the protein levels of FASN, SREBP1, and PI3K-AKT pathway components in tumor tissues." (PMID 40942159, 2025). "Lipid-targeting (e.g., FASN, Acetyl-CoA carboxylase (ACC), Stearoyl-CoA desaturase 1 (SCD1) inhibitors) acts as a metabolic trap: impairing tumour-lipid supply, altering membrane composition and increasing vulnerability to immune attack." (PMID 41394868, 2025). "The oncogenic protein CSN6 binds FBXW7β, enhances its autoubiquitination and degradation, and stabilizes FASN, thereby activating the EGF–CSN6–FASN axis to promote tumor growth." (PMID 41359051, 2025).